HGF (hepatocyte growth factor)
Diseases named in the same sentence as HGF in open-access papers (continued):
Sharing a sentence is not in itself a finding about the gene and the disease.
pancreatic cancer (continued). "To understand how inhibition of the HGF/MET pathway in pancreatic cancer cells influences stroma activation, we performed a transcriptome analysis by RNA-sequencing-based gene expression analysis (RNAseq)." (PMID 34298732, 2021). "We previously demonstrated that HGF/c-Met pathway inhibition is effective at minimising and even eliminating metastasis in early as well as advanced models of pancreatic cancer." (PMID 34199452, 2021). "Meanwhile, IL-1α can enhance the metastatic potential of pancreatic tumor cells by maintaining the constitutive activation of nuclear factor κ-B (NFκB), promoting the secretion of hepatocyte growth factor (HGF), and can facilitate angiogenesis." (PMID 34187428, 2021). "It is overexpressed in pancreatic cancer and increases the cancer invasiveness through the hepatocyte growth factor c-Met pathway." (PMID 33505535, 2021). "To this end, we compared data obtained by large-scale analysis of gene expression in pancreatic cancer cells grown in the presence of HGF versus cells grown in the presence of HGF and treated with specific inhibitors of HGF/MET signaling." (PMID 34298732, 2021). "In view of these findings, there is continuous research on targeting HGF-MET signaling in pancreatic cancer with MET overexpression." (PMID 34479614, 2021). "It has been previously shown that activation of the MET receptor by its ligand, the hepatocyte growth factor (HGF), modulates the tumor-stroma cross-talk in models of pancreatic cancer." (PMID 34298732, 2021). "In this study, we investigated the effect of HGF/MET axis modulation on pancreatic-cancer-cell signature, focusing on the differential expression of TNC." (PMID 34298732, 2021). "In mouse models of pancreatic cancer, HGF inhibitors reduce tumor growth, invasion, and distant metastasis." (PMID 32670371, 2020). "In pancreatic cancer patients, elevated serum HGF levels have been reported to correlate with disease progression, and tumour expression of c-MET to be associated with poor survival." (PMID 33271944, 2020). "Pancreatic cancer patients with high c-Met and HGF expression levels tend to show poor prognosis and low survival rates." (PMID 33195182, 2020). "Recent studies have also demonstrated that PSCs facilitate perineural invasion of pancreatic cancer and this process is mediated via the HGF/c-MET pathway." (PMID 33271944, 2020). "While cancer-associated PSCs secrete hepatocyte growth factor (HGF), its receptor c-MET is present on pancreatic cancer cells." (PMID 32116785, 2020). "Given that a majority of patients are diagnosed at an advanced stage, it would be essential to investigate the effect of HGF/c-MET inhibition in combination with gemcitabine in a model of advanced pancreatic cancer." (PMID 32203220, 2020). "Its clinical relevance to pancreatic cancer has also been demonstrated, with various studies reporting on the overexpression of MET in pancreatic cancers and a correlation between elevated serum levels of HGF and aggressive PDAC phenotypes." (PMID 32485915, 2020). "Similar observations were made in pancreatic cancer wherein HGF was found to be secreted predominantly by PSCs and the receptor c-MET was expressed by cancer cells and endothelial cells." (PMID 33271944, 2020). "Most studies examining the in vitro effects of HGF itself on pancreatic cancer growth and invasion have been limited to cancer cells alone, and have not included stromal cells or PSCs." (PMID 33271944, 2020). "The current review discusses the role of the MET/HGF axis in tumour progression and dissemination of pancreatic cancer." (PMID 33271944, 2020). "A major candidate factor regulating stromal-tumour interactions in pancreatic cancer is the hepatocyte growth factor (HGF) also known as scatter factor (SF)." (PMID 33271944, 2020). "Others have found that knockdown of MSP-RON signaling delays tumor progression and enhances HGF-MET signaling in pancreatic cancer cell lines." (PMID 31867280, 2019).
pancreatic cancer (continued). "The authors reported that NMU, by inducing c-Met, increased cell motility and invasiveness as well as hepatocyte growth factor (HGF)-induced scattering of pancreatic cancer cells." (PMID 31492042, 2019). "NRP1 interacts with MET and increases the ability of HGF to stimulate pancreatic carcinoma cell invasion along with the proliferation and survival of gliomas." (PMID 30871059, 2019). "Since the pioneer studies published in 1995, the MET/HGF system has gained growing attention with respect to its role in the pathogenesis of pancreatic cancer." (PMID 30544501, 2018). "We now demonstrate that human pancreatic cancer cells elicit both an intracellular signalling and migratory response to HGF stimulation." (PMID 28205613, 2017). "Recent reports have also supported the ability of PSCs to secrete HGF, which in turn can stimulate proliferation and migration of vascular endothelial cells and pancreatic cancer cells." (PMID 29069737, 2017). "Activation of Met by HGF has been shown to promote both growth and invasion of human pancreatic cancer cells." (PMID 29069737, 2017). "Using both in vivo and in vitro approaches, this study has provided novel evidence to indicate that stromal reprogramming (by inhibiting the HGF/c-MET pathway) combined with chemotherapy significantly reduces pancreatic cancer progression." (PMID 29100344, 2017). "We also observed the enrichment of several other canonical pathways such as TGF-β signaling, HGF signaling, apoptosis signaling, cell adhesion and Wnt pathway, which are also important in pancreatic cancer." (PMID 28423671, 2017). "In this study we have demonstrated that the highly invasive pancreatic cancer cell line, PaTu8988T, exhibits a biochemical and migratory response to HGF stimulation." (PMID 28205613, 2017). "For example, USP15 was one of twelve DUBs identified from an siRNA screen that regulates the hepatocyte growth factor (HGF)-dependent cell scattering response in non-small cell lung cancer and pancreatic cancer cells." (PMID 28074857, 2017). "Our data suggests that both PAK4 and PI3K have functionality during the migration of pancreatic cancer cells in the presence of HGF." (PMID 28205613, 2017). "Fibroblasts and pancreatic cancer cells can communicate through the HGF/Met pathway, as shown where HGF secreted by tumor-derived fibroblasts stimulated pancreatic cancer cell invasion." (PMID 29069737, 2017). "It has also been shown that HGF-secretion from fibroblasts is increased by IL-1α or by co-culture with IL-1α-expressing pancreatic cancer cells." (PMID 29069737, 2017). "Our data suggests that both PAK4 and PI3K are essential components of the migratory response of pancreatic cancer cells to HGF both in 2D and 3D." (PMID 28205613, 2017). "Recently inhibition of the HGF/Met pathway mediating tumor-stroma interactions was reported to inhibit local tumor growth in an orthotropic pancreatic cancer model." (PMID 29069737, 2017). "Previously, some studies have reported stimulatory effects on pancreatic cancer cell migration by HGF secreted from immortalized fibroblast cells lines or primary fibroblasts from pancreatic tumors." (PMID 29069737, 2017). "In contrast, knockdown of PHLPP significantly enhanced the ability of pancreatic cancer cells to migrate in response to HGF." (PMID 26760962, 2016). "Both HGF and VEGFα have angiogenic properties in pancreatic cancer and promote tumor growth and invasion." (PMID 26849807, 2016). "HGF and its receptor counterpart are emerging as an attractive target to be exploited not only in early detection of pancreatic cancer, but also as a target for chemotherapy." (PMID 26404380, 2015). "In conclusion, these results indicate that cMET expression is involved in resistance to gemcitabine and INC280 effectively inhibits HGF-induced effects in gemcitabine-resistant pancreatic cancer cell lines." (PMID 25884642, 2015).
pancreatic cancer (continued). "Combining promising c-MET and HGF antagonists along with strategic utilization of current treatment regimens leave the pancreatic cancer community with an expectant outlook for the future of medical intervention." (PMID 26404380, 2015). "A major factor regulating desmoplasia and subsequently promoting chemoresistance in pancreatic cancer is hepatocyte growth factor (HGF), the sole ligand for c-MET (mesenchymal-epithelial transition), an epithelial tyrosine kinase receptor." (PMID 26404380, 2015). "Because the HGF/c-MET signaling is one of the most frequently dysregulated pathways in pancreatic cancer, targeting of this pathway received much attention recently." (PMID 25909285, 2015). "Taken together, our results show that treatment with INC280 efficiently abrogates HGF-induced motility and oncogenic signaling in pancreatic cancer cell lines in vitro." (PMID 25884642, 2015). "This phenomenon was demonstrated in pre-clinical studies, where patient-derived stromal tissues expressing HGF correlated with enhanced invasion of pancreatic cancer cells with only high expression of c-Met." (PMID 26404380, 2015). "Treatment with INC280 impairs activation of signaling intermediates in pancreatic cancer cells and ECs, particularly when cells were stimulated with hepatocyte growth factor (HGF)." (PMID 25884642, 2015). "This review provides a comprehensive analysis of HGF and its promising potential as a chemotherapeutic target for pancreatic cancer." (PMID 26404380, 2015). "Our results show that cMET inhibition impairs activation of HGF-induced oncogenic signaling intermediates in human and murine pancreatic cancer cell lines." (PMID 25884642, 2015). "The importance of rising HGF in pancreatic cancer in vivo is suggested by studies that have demonstrated the rise of HGF serum levels as the disease advances." (PMID 26404380, 2015). "HIF-dependent pathways activate MET in pancreatic tumor cells, while stroma-secreted HGF facilitates cell motility from the hypoxic regions of the tumors to the oxygen-rich distant organs." (PMID 26404380, 2015). "So, although there is a suggested link between HGF and multiple cytokines that promote a desmoplastic reaction in the tumor microenvironment, the role of HGF through similar pathways in pancreatic cancer is a topic for future research endeavors." (PMID 26404380, 2015). "Studies in pancreatic cancer revealed that inhibiting TGF-β production by cancer cells facilitates fibroblast-derived HGF-induced tumor cell invasion." (PMID 26404380, 2015). "In pancreatic carcinoma cells, HGF seems to have a potent role in invasion and metastasis by exerting its antianoikis effect through phosphatidylinositol 3-kinase pathway." (PMID 26435753, 2015). "Signaling by Hedgehog proteins or hepatocyte growth factor (SF/HGF) play important developmental roles, and both pathways are deregulated in pancreatic cancer." (PMID 25265995, 2014). "This is supported by the finding that the invasive ability of pancreatic tumor cells decreased under HGF stimulation." (PMID 22962849, 2012). "It has been reported that MUC1 over-expressing pancreatic tumor cells have higher c-Met signaling activity and a greater tendency to metastasize when low levels of HGF are present in the tumor microenvironment." (PMID 22962849, 2012). "Two recent studies independently demonstrated that NRP1 physically binds c-MET, and potentiates c-MET activation in response to HGF stimulation in human glioma and pancreatic cancer cells." (PMID 20085644, 2010). "An enhanced expression of Rac1 has been documented for pancreatic cancer tissue and pancreatic carcinoma cell lines and active Rac1 is necessary for cell migration and invasion in pancreatic tumours after HGF or LPA-stimulation." (PMID 19737400, 2009).
pancreatic cancer (continued). "We report here the induction of highly motile and invasive properties in human pancreatic cancer cells by hepatocyte growth factor (HGF) and blockage of these properties by NK4, a newly identified antagonist for HGF." (PMID 11259105, 2001). "Consistently, the ascitic fluid in patients who had undergone pancreatic cancer surgery contained high levels of HGF." (PMID 11259105, 2001). "Similarly, adipocyte‐derived factors, including HGF and glutamine, accelerate murine and human pancreatic cancer cell proliferation." (PMID 40751595, 2025). "Therefore, targeting the HGF/c-MET signaling pathway appears promising for the development of innovative drugs for pancreatic cancer treatment." (PMID 38473413, 2024). "Furthermore, they play a crucial role in the pancreatic cancer environment by releasing factors like SDF-1, HGF, galectin-1, TGFβ, and IL-6, promoting pancreatic cancer progression." (PMID 39199647, 2024). "In addition, hepatocyte growth factor (HGF), fibrinogen, and inflammatory markers such as C-reactive protein (CRP) and interleukin-6 (IL6) have been linked to pancreatic cancer instances." (PMID 39200847, 2024). "While 33.3% of the patients with pancreatic cancer were found in the high HGF group, 46.2% of the patients with ampullary cancer were found in the high HGF group, and 72.7% of the patients with biliary tract cancer were in the high HGF group (P = .022)." (PMID 36789987, 2023). "HGF is known to exacerbate pancreatic cancer cell ferroptosis resistance." (PMID 37681908, 2023). "Based on this, we believe that savolitinib, a MET TKI targeting the MET/HGF pathway, may be beneficial in the treatment of pancreatic cancer, and further studies may be conducted in the future." (PMID 37835402, 2023). "In summary, this study indicated that pancreatic cancer cells could activate pancreatic stellate cells, promote their secretion of HGF, enhance the antioxidant capacity of pancreatic cancer cells, and mediate ferroptosis resistance in pancreatic cancer." (PMID 35693705, 2022). "Additionally, knockdown of c-MET reduced GSH content and increased MDA and lipid ROS production in activated PSC coculture and HGF-treated pancreatic cancer cells in the presence of ferroptosis inducers." (PMID 35693705, 2022). "The activated PSCs could secrete HGF, which enhanced the antioxidant capacity of pancreatic cancer cells, thereby resisting ferroptosis." (PMID 35693705, 2022). "To further confirm our in vitro observations, we next investigated whether activated PSCs and HGF have a role in promoting ferroptosis resistance in pancreatic cancer in vivo." (PMID 35693705, 2022). "Given that suppressing mTOR expression inhibits PNI in pancreatic cancer, we speculated whether mTOR is required for the HGF/c-Met signaling pathway to exert its promoting effects on PNI in pancreatic cancer." (PMID 35449152, 2022). "Furthermore, the wound healing assay revealed that activating c-Met by recombinant HGF promotes the healing abilities of pancreatic cancer cell lines." (PMID 35449152, 2022). "Associations between some proteins [e.g. matrix metalloproteinase-7 (MMP7), hepatocyte growth factor (HGF) and tumour necrosis factor receptor superfamily member 9 [TNFRSF9)] and risk of pancreatic cancer were time-varying, with higher levels associated with higher short-term risk." (PMID 35064782, 2022). "Furthermore, activating the HGF/c-Met/mTOR signaling pathway in pancreatic cancer promotes the growth of DRG axons in the cancer cells-DRG coculture model." (PMID 35449152, 2022). "Furthermore, the expression of NGF was detected by western blotting revealed that activating the HGF/c-Met signaling pathway promotes NGF expression in the pancreatic cancer cell lines PANC-1 cells and BxPC-3 cells." (PMID 35449152, 2022). "Furthermore, blocking the HGF/c-Met/mTOR signaling pathway by knocking down the expression of mTOR inhibits the invasion and migration of pancreatic cancer cells." (PMID 35449152, 2022).
pancreatic cancer (continued). "Interestingly, administration of an HGF-targeting antibody (AMG-102) in experimental models of pancreatic cancer was able to produce a phenotypic reprogramming of stromal cells that ultimately led to decreased collagen deposition." (PMID 34298732, 2021). "However, few therapeutic outcomes have been obtained from these studies because of HGF-MET-targeting drug resistance in pancreatic cancer." (PMID 34479614, 2021). "Two metastatic models were generated in mice knocked-in by the human HGF gene: (i) orthotopic transplantation of pancreatic cancer cells; (ii) subcutaneous injection of primary cells derived from a cancer of unknown primary." (PMID 33446252, 2021). "Targeting the HGF/c-Met pathway, especially using rilotumumab, impacts angiogenesis as evidenced by a decrease in the proliferation of endothelial cells and tube formation in pancreatic cancer and glioma." (PMID 34771724, 2021). "Simultaneous inhibition of HGF and c-MET combined with gemcitabine is more effective in reduction of tumor volume in an orthotopic model of pancreatic cancer than chemotherapy alone, indicating a critical role of the HGF/c-MET pathway in PSC–cancer cell interactions." (PMID 32116785, 2020). "Furthermore, enhanced glycolytic metabolism in pancreatic cancer cells can also be induced by paracrine hepatocyte growth factor (HGF) from PSCs." (PMID 32122374, 2020). "Our pancreatic cancer treatment strategy included chemotherapy and HGF/c-MET inhibition." (PMID 32203220, 2020). "The MET/HGF axis is involved in the complex crosstalk between tumor and stroma, especially in the interaction between cancer cells and activated PSCs, thereby favors the progression and metastasis of pancreatic cancer." (PMID 33008376, 2020). "In pancreatic tumors, the situation might be even more complicated, e.g., because stromal cells themselves produce Hedgehog and HGF that support the tumor growth." (PMID 30201866, 2018). "At present, the relationship between pancreatic cancer and miRNAs-HGF/c-MET is being explored." (PMID 30360560, 2018). "Since a cell growth effect of HGF has been described in human pancreatic cancer cell lines we performed cell count analysis but could not confirm a significant boost in cell proliferation." (PMID 29520499, 2018). "We therefore tested whether the PI3K pathway also influences pancreatic cancer cell migration mediated by HGF." (PMID 28205613, 2017). "In the present study, we aimed to determine the ability of PSC populations derived from different patients to stimulate DNA synthesis and migration in pancreatic cancer cells, and, specifically, to what extent HGF secretion from PSCs is involved in the effects." (PMID 29069737, 2017). "b) reduction of uPA production by cancer cells, thus preventing further HGF activation (thus inhibiting the positive feedback loop).c) blockade of stemness in cancer cells (given that c-MET is recognized to be a stem cell marker in pancreatic cancer)." (PMID 29100344, 2017). "However, the functionality of PAK4 in pancreatic cancer and the contribution made by HGF signalling to pancreatic cancer cell motility remain to be elucidated." (PMID 28205613, 2017). "Furthermore, we demonstrate that pancreatic cancer cells have a specific motility response to HGF both in 2D and 3D physiomimetic organotypic assays; which can be suppressed by inhibition of PI3K." (PMID 28205613, 2017). "Recent studies also indicate that the signaling axis of HGF and its receptor c-Met plays an important role in the interaction between PDAC-associated microenvironment and PDAC, therefore promoting desmoplasia and chemoresistance in pancreatic cancer." (PMID 28388589, 2017). "Increased MET expression and HGF-dependent invasion under hypoxia has been described years ago and has been subsequently confirmed by other studies conducted in several model systems, including glioblastoma and pancreatic cancer." (PMID 28445144, 2017).